IGHGP (immunoglobulin heavy constant gamma P (non-functional))
Synonyms: formerly IGHGP1
Gene: Gene (Ensembl biotype IG_C_pseudogene) on chromosome 14 (105,664,633 to 105,669,843, reverse strand). Ensembl gene ENSG00000253755.
Diseases named in the same sentence as IGHGP in open-access papers:
IGHGP is named in the same sentence as 1 disease in open-access papers, as found by Europe PMC text mining. Sharing a sentence is not in itself a finding about the gene and the disease.
IGHGP shares sentences with these, for which no sentence is quoted: tumor (1 paper).